CRX (cone-rod homeobox)
Description:
Transcription factor that binds and transactivates the sequence 5'-TAATC[CA]-3' which is found upstream of several photoreceptor-specific genes, including the opsin genes. Acts synergistically with other transcription factors, such as NRL, RORB and RAX, to regulate photoreceptor cell-specific gene transcription. Essential for the maintenance of mammalian photoreceptors.
Synonyms: CORD2; CRD; LCA7; OTX3
Tractability: No criterion of Open Targets' tractability assessment is met for any kind of drug.
Gene: Protein-coding gene on chromosome 19 (47,819,779 to 47,843,330, forward strand). Ensembl gene ENSG00000105392.
Subcellular location: Nucleus
Subcellular location (Human Protein Atlas): Nucleoli fibrillar center; Cytosol; Nucleoplasm; Primary cilium
Gene Ontology:
Molecular function: DNA-binding transcription activator activity, RNA polymerase II-specific; leucine zipper domain binding; protein binding; RNA polymerase II cis-regulatory region sequence-specific DNA binding; sequence-specific double-stranded DNA binding; DNA-binding transcription activator activity; DNA-binding transcription factor activity; DNA-binding transcription factor activity, RNA polymerase II-specific; nuclear receptor binding; RNA polymerase II transcription regulatory region sequence-specific DNA binding; RNA polymerase II-specific DNA-binding transcription factor binding; chromatin binding; DNA binding
Biological process: positive regulation of transcription by RNA polymerase II; animal organ morphogenesis; regulation of DNA-templated transcription; regulation of transcription by RNA polymerase II; visual perception
Cellular component: chromatin; nucleus; RNA polymerase II transcription regulator complex; transcription regulator complex
Genetic constraint (gnomAD): Loss-of-function variants: 5 observed, 15.63 expected, observed/expected ratio (o/e) 0.32, 90% interval 0.17 to 0.67. The upper end of that interval is the gene's LOEUF score, 0.67, which puts it in group 2 of 6, group 1 being the genes least tolerant of losing a copy. Missense variants: 351 observed, 411.53 expected, observed/expected ratio (o/e) 0.85, 90% interval 0.78 to 0.93. Synonymous variants: 179 observed, 180.86 expected, observed/expected ratio (o/e) 0.99, 90% interval 0.88 to 1.12.
Gene-disease validity (ClinGen):
ClinGen rates the evidence that CRX causes each of these diseases.
cone-rod dystrophy 2 (autosomal dominant): Definitive.
Homologues: Orthologues: macaque CRX (100% identical), chimpanzee CRX (99% identical), guinea pig CRX (99% identical), rat Crx (97% identical), dog CRX (97% identical), mouse Crx (97% identical), pig CRX (82% identical), tropical clawed frog crx (58% identical), zebrafish otx5 (57% identical). Paralogues in human: OTX2 (54% identical), OTX1 (48% identical), PAX7 (24% identical), ARX (24% identical), PAX3 (24% identical), PHOX2B (22% identical), RAX (22% identical), ALX4 (22% identical), ARGFX (22% identical), DRGX (22% identical), PHOX2A (22% identical), PITX2 (22% identical), and 38 more.
Diseases named in the same sentence as CRX in open-access papers:
CRX is named in the same sentence as 56 diseases in open-access papers, as found by Europe PMC text mining. Sharing a sentence is not in itself a finding about the gene and the disease. The quoted sentences say what the papers report.
Leber congenital amaurosis (31 papers, 2006 to 2026). Leber congenital amaurosis (LCA) is a retinal dystrophy defined by blindness and responses to electrophysiological stimulation (Ganzfeld electroretinogram (ERG)) below threshold, associated with severe visual impairment within the first year of life. "CRX-associated retinopathies can produce variable phenotypes, including Leber congenital amaurosis (LCA), maculopathy (M), cone-rod dystrophy (CRD), and rod-cone dystrophy (RCD), such as retinitis pigmentosa (RP)." (PMID 41595470, 2026). "For example, a CRX K50N variant associated with Leber congenital amaurosis both increased CRX cooperativity and altered DNA binding specificity, much like we found using the CRX K50Q variant." (PMID 41279221, 2025). "To date, there is only one disease associated variant in the 4th position as CRX E4K is associated with Leber congenital amaurosis." (PMID 41279221, 2025). "CRX is essential for proper photoreceptor development within the eye and genetic variants in CRX have been associated with cone-rod dystrophy, retinitis pigmentosa, macular dystrophy, and Leber congenital amaurosis." (PMID 41279221, 2025). "Mutations in the CRX sequence or changes in its binding sites lead to several retinal diseases, including Leber Congenital Amaurosis, Cone-rod Dystrophies, and Retinitis Pigmentosa, as well as changes in chromatin remodeling in specific target sites." (PMID 40758714, 2025). "Coding variants in CRX have been associated with at least three types of retinopathies that result in blindness, including Leber Congenital Amaurosis (LCA), Cone-rod Dystrophies (CoRD), and Retinitis Pigmentosa (RP)." (PMID 38414750, 2024). "Mutations in the human CRX gene are associated with various blinding diseases ranging from mild macular dystrophy to severe conditions like Leber congenital amaurosis (LCA), cone-rod dystrophy (CRD), and RP." (PMID 39199291, 2024). "CRX is important for photoreceptor maintenance, as CRX mutations result in cone-rod dystrophy or Leber’s congenital amaurosis, which causes photoreceptor degeneration and vision loss." (PMID 35493094, 2022). "Cases of Leber congenital amaurosis caused by mutations in CRX (LCA7) exhibit an early form of the disease and show signs of significant photoreceptor dysfunction and eventual loss." (PMID 34653402, 2021). "For example, mutations in CRX cause both early-onset Leber congenital amaurosis (LCA) and progressive CRD or RP, where disease progresses over time." (PMID 25650393, 2015). "In humans, mutations in CRX are associated with retinal degeneration diseases such as cone-rod dystrophy-2, retinitis pigmentosa (RP), and Leber congenital amaurosis (LCA)." (PMID 21602925, 2011). "CRX coding variants are associated with at least three forms of inherited retinal disorders (IRDs) that cause blindness, including Leber congenital amaurosis 7 (LCA7, OMIM: 613829), Cone-rod dystrophy 2 (CoRD2, OMIM: 120970), retinitis pigmentosa (RP, OMIM: 268000)." (PMID 38414750, 2024). "To date, approximately 100 CRX mutations have been identified to cause dominant retinal degeneration with varied severity in clinical phenotype, including Macular Dystrophy, Retinitis Pigmentosa, Cone-Rod Dystrophy and Leber Congenital Amaurosis." (PMID 38049871, 2023). "Protein-coding sequence variants in human CRX have been associated with inherited retinal diseases (IRDs) that affect photoreceptors: Leber congenital amaurosis (LCA), cone–rod dystrophy (CoRD), and retinitis pigmentosa (RP) (OMIM:602225)." (PMID 37963072, 2023). "Mutations in human CRX are associated with the dominant retinopathies Retinitis Pigmentosa (RP), Cone-Rod Dystrophy (CoRD) and Leber Congenital Amaurosis (LCA), with variable severity." (PMID 24516401, 2014). "In fact, at this end of the spectrum, there have been a few reports of dominant Leber congenital amaurosis (LCA) caused by CRX mutations, a condition which is usually recessive, as well as a few RPs." (PMID 17270046, 2007).
Leber congenital amaurosis (continued). "In addition, mutations of human CRX have been demonstrated to be associated with three types of photoreceptor diseases: autosomal dominant cone-rod dystrophy 2, autosomal dominant-type retinitis pigmentosa, and Leber's congenital amaurosis (LCA)." (PMID 16539743, 2006). "CRX genetic variants may be responsible for different clinical phenotypes, including cone–rod dystrophy, Leber congenital amaurosis (LCA), macular degeneration, and RP." (PMID 38792980, 2024). "Induced pluripotent stem cell (iPSC)-based models have been used to model several retinal degenerations such as RP, Usher’s syndrome, Leber congenital amaurosis (LCA), and CRX-associated LCA7." (PMID 38661530, 2024). "CRX variants can lead to not only dominant CORD but also dominant retinitis pigmentosa and Leber congenital amaurosis." (PMID 38028590, 2023). "To date, 139 pathogenic CRX variants have been associated with a wide range of inherited retinal dystrophy (IRD) phenotypes, including cone-rod dystrophy (CORD), Leber congenital amaurosis (LCA), retinitis pigmentosa (RP), and macular dystrophy (MD)." (PMID 37239417, 2023). "CRX may be mutated in three forms of human blindness; Leber congenital amaurosis (LCA), cone-rod degeneration (CRD) and retinitis pigmentosa (RP)." (PMID 29568065, 2018). "For example, mutations in ABCA4, CRX, CERKL, PROM1, SEMA4A, GUCY2D can cause either CCRD, but also RP or Leber congenital amaurosis (LCA)." (PMID 26103963, 2015). "Mutations in the human CRX gene have been associated with dominant forms of retinal degenerative diseases such as retinitis pigmentosa, cone-rod dystrophy (CoRD) and Leber congenital amaurosis (LCA), with varied age of onset and severity." (PMID 26324254, 2015). "The diversity of CRX-associated phenotypes mirrors the underlying genetic heterogeneity and manifests as macular dystrophy (M), cone or cone–rod dystrophies (CRD), rod-cone dystrophy (RCD) or retinitis pigmentosa (RP), and Leber congenital amaurosis (LCA)." (PMID 41595470, 2026). "Additionally, a recent study employed a promoter derived from the human cone-rod homeobox protein (CRX) to achieve highly specific photoreceptor expression in an organoid model derived from a patient with Leber congenital amaurosis." (PMID 38474133, 2024). "Because CRX appears to interact with many retinal genes, mutations in the CRX gene are responsible for a wide phenotypic spectrum of retinal dystrophies, including cone–rod dystrophy type 2 (CORD2), Leber congenital amaurosis (LCA), pattern dystrophy (PD), macular degeneration, and RP." (PMID 38792980, 2024). "Mutations in the photoreceptor transcription factor gene cone-rod homeobox (CRX) lead to distinct retinopathy phenotypes, including early-onset vision impairment in dominant Leber congenital amaurosis (LCA)." (PMID 33513359, 2021). "Mutations in human CRX (NCBI Reference Sequence: NG_008605.1) have been associated with autosomal dominant forms of the retinal degenerative diseases Retinitis Pigmentosa (adRP), Cone-Rod Dystrophy (adCoRD) and Leber Congenital Amaurosis (adLCA), with different ages of onset and severity." (PMID 24516401, 2014). "Variants in CRX (OMIM: 602225) have been shown to cause several inherited retinal diseases, including retinitis pigmentosa (RP), cone-rod dystrophy (CoRD), and Leber congenital amaurosis (LCA)." (PMID 38355306, 2024). "ROs have also been used to identify the disease mechanisms of Leber’s congenital amaurosis (LCA)-related RPE65, CEP290, AIPL1 and CRX." (PMID 34719743, 2021). "In another study including 18 patients from 11 families, multimodal retinal imaging combined with electrophysiology identified 4 Leber congenital amaurosis (LCA), 2 retinitis pigmentosa (RP), 6 COD/CORDs, and 6 “atypical maculopathy” patients carrying the same heterozygous CRX mutation." (PMID 31574917, 2019).
cone-rod dystrophy (18 papers, 2008 to 2026). Inherited retinal dystrophies that belong to the group of pigmentary retinopathies. "In contrast, a CRX E42A variant associated with cone rod dystrophy was found to disrupt cooperativity and behaved similarly as the PHOX2B E42Q and ALX4 E42A variants." (PMID 41279221, 2025). "We performed a similar analysis on variants in CRX, which has been reported to have R2Q, R3Q, and R3W variants associated with cone rod dystrophy." (PMID 41279221, 2025). "Ataxin-7 interacts with CRX, a transcription factor regulating photoreceptor genes known to cause cone-rod dystrophy." (PMID 38976217, 2024). "Pathogenic CRX mutations are associated with macular dystrophy, cone-rod dystrophy (CRD), retinitis pigmentosa (RP), and LCA." (PMID 37181651, 2023). "Inappropriate interactions between expanded ataxin-7 and CRX are known to cause the phenotype similar to cone-rod dystrophy." (PMID 32973440, 2020). "Mutations in the human CRX gene have been associated with the retinal degeneration diseases Retinitis Pigmentosa (RP), Cone-Rod Dystrophy (CoRD) and Leber Congential Amaurosis (LCA)." (PMID 24516401, 2014). "Treatment of cone photoreceptors is of relevance because mutations in CRX also cause milder adult-onset cone-rod dystrophies and macular dystrophies, which could potentially benefit from gene therapy treatment described here." (PMID 33513359, 2021). "One of the causative genes in cone-rod dystrophies is CRX mutations." (PMID 32973440, 2020). "Humans with CRX mutations demonstrate cone-rod retinal dystrophy." (PMID 32842706, 2020). "Additionally, a patient with a clinical diagnosis of either cone or cone-rod dystrophy was found to have an approximately 85 kb deletion of the CRX gene, which is implicated in autosomal dominant cone-rod retinal dystrophy 2, a very good fit for the patient’s phenotype." (PMID 30557390, 2018). "Cone-rod homeobox (CRX) is a transcription factor found in photoreceptor cells and mutations have been associated with cone-rod dystrophy." (PMID 33105605, 2020). "Three of the genes, CNGB3, CNGA3 and GNAT2, involved in cone degeneration and seven genes and loci, ABCA4, RDH5, CORD8, CORD9, RPGRIP1, GUCY2D and CRX, reported to be involved in cone-rod dystrophies were studied." (PMID 18593457, 2008). "The genes involved in cone degeneration, CNGB3, CNGA3 and GNAT2, and the genes involved in cone-rod dystrophy, ABCA4, RDH5, Cord8, Cord9, RPGRIP1, GUCY2D and CRX, were all excluded from being involved in the cone-rod dystrophy described in this family of SWHD." (PMID 18593457, 2008). "In addition to causing cerebellar atrophy, polyglutamine-expanded ataxin-7 disrupts transcription of genes regulated by the cone-rod homeobox protein (CRX), resulting in a marked cone-rod dystrophy." (PMID 35422034, 2022).
retinoblastoma (17 papers, 2009 to 2026). A malignant tumor that originates in the nuclear layer of the retina. "From a diagnostic standpoint, we find that >90% of retinoblastoma and >90% of pineal parenchymal tumors display significant intranuclear expression of CRX while none of the tumors entering the differential diagnosis of pineal masses display intranuclear CRX immunoreactivity." (PMID 19936203, 2009). "Here, we evaluate the feasibility of cell-free RNA (cfRNA)- and circulating tumor cell RNA (ctcRNA)-based liquid biopsy for the sensitive detection of disseminated retinoblastoma using digital PCR (dPCR) targeting the retina-specific markers CRX and RBP3." (PMID 42196162, 2026). "Staining for CRX was strongly positive at d35 in RB1ko, consistent with the findings in retinoblastoma." (PMID 35565295, 2022). "To explore further the heterogeneity in terms of cone differentiation in retinoblastoma, we studied by immunohistochemistry the distribution of an early photoreceptor marker (CRX), and a later marker specific to the cone lineage (ARR3)." (PMID 34552068, 2021). "Retinoblastoma cell line Y79 and primary retinoblastoma cells expressed the cone-rod homeobox protein (CRX), a photoreceptor-specific marker." (PMID 34639028, 2021). "All tumors, regardless of the subtype, expressed the photoreceptor marker CRX in agreement with retinoblastoma being derived from cone-committed cells." (PMID 34552068, 2021). "Examining retinal proteins in retinoblastoma has shown that transcription factors cone-rod homeobox protein (CRX) and homeobox protein OTX2, which specify fate decision for photoreceptors, are widely expressed in retinoblastoma." (PMID 32824373, 2020). "CRX (Cone-rod homeobox protein) has been proposed as a sensitive and specific clinical marker and potential therapeutic target in retinoblastoma and pineoblastoma, and is essential for growth of tumor cells with photoreceptor differentiation." (PMID 28592245, 2017). "Previous studies have shown that Crx is upregulated in human retinoblastoma cells after treatment with retinoids, and here we show that a synthetic retinoic acid also increases CRX gene and protein expression in human RPE cells." (PMID 21738400, 2011). "These same studies in the retina had concluded that retinoblastomas represented a bias towards cone differentiation, and the presence of strong CRX staining supports this given its more specific role in development of cone photoreceptors." (PMID 19936203, 2009). "Little is known about CRX expression or function in human cancer, although several studies have described its expression in retinoblastoma cell lines." (PMID 19936203, 2009). "Immunohistochemical analysis of 22 retinoblastomas and 13 pineal parenchymal tumors demonstrated strong expression of CRX in over 95% of these tumors." (PMID 19936203, 2009). "CRX protein expression was evaluated by immunohistochemistry in 22 enucleation specimens for histologically confirmed retinoblastoma." (PMID 19936203, 2009). "In the primary retinoblastoma cells isolated from this patient, as well as the Y79 cells, a commercially available retinoblastoma cell line, the photoreceptor specific protein CRX expression was detectable, confirming that these cells were developed from photoreceptors." (PMID 34639028, 2021). "Indeed, RA induces upregulation of cone-rod homeobox (Crx) expression in retinoblastoma cells, a pineal- and retina-specific transcription factor which is required for the intact diurnal rhythm in Aanat mRNA." (PMID 29520716, 2018). "To further determine the correlation of p16INK4a expression with the level of cell differentiation, we detected the expression of both the photoreceptor differentiation marker CRX and the cell proliferation marker Ki67 in consecutive sections of retinoblastoma samples." (PMID 25499675, 2014).
retinoblastoma (continued). "Our identification of retinoblastoma and medulloblastoma cell lines with CRX expression also represents an opportunity for performance of further functional studies of CRX in these specific human cell line systems given the lack of readily available model systems for these cancers." (PMID 19936203, 2009). "Our study suggests CRX might represent just such a target in retinoblastoma, pineoblastoma, and possibly even a subset of medulloblastoma." (PMID 19936203, 2009). "The presence of photoreceptor cells in retinoblastoma has long been under debate since tumors contain rosette structures suggestive of primitive photoreceptors and clinical diagnosis is based on positivity for the photoreceptor marker CRX and the proliferation marker Ki67." (PMID 35565295, 2022). "Finally we find that CRX is a new sensitive and specific marker for retinoblastoma and pineal parenchymal tumors that should be useful in the diagnostic evaluation of pineal masses when used as part of a panel of immunohistochemical markers including synaptophysin and GFAP." (PMID 19936203, 2009). "The high expression of OTX2 and CRX in RB tumors and cell lines suggested that retinoblastomas may originate from cells normally expressing these transcription factors, such as bipolar cells or photoreceptor precursors." (PMID 38069286, 2023). "Of three cone-specific markers, CRX, RXR-γ and TRβ−2, RXR-γ was expressed at an eightfold higher level in retinoblastoma compared to matched retina." (PMID 20664703, 2010). "CRX immunostaining was negative in the regions of optic nerve adjacent to the retinoblastoma (lower right portion of field)." (PMID 19936203, 2009). "We transfected the rho-Gluc reporter with either shEGFP, shPIAS2_49 or shPIAS2_50, with and without the CRX and NRL expression vectors, into monkey kidney (COS7) and two human retinoblastoma cell lines (WERI-Rb, Y79)." (PMID 27977714, 2016).